POLE (DNA polymerase epsilon, catalytic subunit)
Diseases named in the same sentence as POLE in open-access papers (continued):
Sharing a sentence is not in itself a finding about the gene and the disease.
tumor (continued). "Notably, POLE mutant, ultra-mutated tumours have greater progression-free survival (PFS) when matched for stage, grade, and morphological subtype, and therefore do not require adjuvant treatment in early stage (I–II) disease." (PMID 37760602, 2023). "Out of the three responders, one had a MMRd tumour, and one harboured a somatic POLE mutation." (PMID 36922497, 2023). "Somatic POLE ED pathogenic variants occur in 7–15% of endometrial cancers, 0.5–8% of colorectal tumors, and more rarely in brain tumors (gliomas), extracolonic gastrointestinal cancers, and other tumor types." (PMID 37848928, 2023). "For CSGs for which germline-focused tumor analysis was recommended only for specific cancer types and age groups, the proportion of variants meeting these recommendations was approximately 1%–4%, except for POLE (22%) and FH (20%)." (PMID 37916805, 2023). "However, a study that used CRISPR to separately engineer different POLE and POLD1 mutations into two different mouse tumor cell lines found that ICI sensitivity was significantly improved in those syngeneic POLE and POLD1 tumors." (PMID 37388540, 2023). "We analyzed mutational signatures from the POLD1/POLH tumor and the POLE tumor." (PMID 37095444, 2023). "However, while POLE/POLD1-mutated CRCs share some features with MSI-H CRCs (such as a high tumor mutation burden), they are typically MSS tumors and are unlikely to account for any of the sporadic MSI-H EOCRC cases in our meta-analysis." (PMID 39132649, 2023). "In the present study, three approaches have been used to substantiate the pathogenicity of the germline POLE c.1373A > T p.(Tyr458Phe) variant: WES of tumor DNA, reporter-based and yeast-based mutagenesis assays and in silico protein modeling based on a homology model." (PMID 36856825, 2023). "Also, the mutational signatures associated with POLE/POLD1 exonuclease domain defects have been reproduced in vitro in tumor PDOs with a POLE hotspot mutation, POLE CRISPR-edited cells and POLD1 patient-derived fibroblasts." (PMID 36756361, 2023). "In addition, POLE mutations are associated with a high tumor mutational burden, which leads to an increased number of mutations in the DNA of the tumor cells." (PMID 38085674, 2023). "Indeed, POLE-mutated patients were characterized by an excellent prognosis, even when a high tumor grade or an advanced stage of disease were present." (PMID 36358847, 2022). "The location of POLE mutations may be the dominant factor determining tumor phenotype and clinical outcome." (PMID 35780178, 2022). "Passenger mutations that accumulate in cells may lead to the slow growth and even death of tumor cells with POLE mutation, which may underlie the favorable prognosis of POLE-mutant tumors." (PMID 35780178, 2022). "Secondly, EC subtypes with high tumor mutational burden (e.g., POLE-mutant/hypermutated and MSI-H) are highly immunogenic and exhibit more tumor-specific neoantigens, resulting in increased CD4 and CD8 tumor-infiltrating lymphocytes (TILs) and a compensatory upregulation of immune checkpoints." (PMID 36119020, 2022). "It shows a cold tumor landscape -low P2 abundance - that is associated with POLE WT patients." (PMID 35217454, 2022). "The tumor with the highest TMB (161.1 mutations/Mb) had a pathogenic POLE variant." (PMID 36335173, 2022). "In conclusion, this thorough molecular characterization of a single patient with multiple tumor lesions unveiled the co-occurrence of germline POLE and PMS2 pathogenic variants (from the maternal and paternal lineage, respectively) predisposing to the development of multiple neoplasms." (PMID 35260767, 2022). "It is likely that POLE mutation has an influence on tumor characteristics." (PMID 35982066, 2022).
tumor (continued). "Since point mutations in PolE produce ultramutation genotypes in tumors, one question is whether these mutations occur in specific oncogenes and/or tumor suppressor genes." (PMID 35326618, 2022). "In this review, we provide a comprehensive overview of this PolE-associated ultramutated tumor." (PMID 35326618, 2022). "It suggests that somatic PolE mutations are early events and may contribute to tumor initiation and good prognosis." (PMID 35326618, 2022). "A higher degree of ITH was detected, as expected, in MMRd CRCs, and in the POLE-mutated tumor." (PMID 33435234, 2021). "Furthermore, the tumor phenotypes and POLE/POLD1 expression levels correlate with tumor mutation burden and tumor driver gene expression according to an analysis of a panel of mutations in 1,392 Chinese patients with cancer." (PMID 34950188, 2021). "The extension of its application to the study of POLE variants is already underway, and this method could be extended to the characterization of all essential tumor suppressor genes in our model, not only within the field of oncology." (PMID 34749799, 2021). "However, when present, POLE/POLD1-mutated cancers are associated with a high tumour mutational burden; hence, their use has also been suggested in predicting efficacy of immunotherapy." (PMID 34694371, 2021). "An increased CD8+ T lymphocyte density in tumor tissues has been reported to be associated with a reduced risk of recurrence, independent of confounding factors, including DNA mismatch repair defects, POLE mutations, and chromosomal instability." (PMID 34604068, 2021). "Collectively, ARID1A loss reportedly promotes mutagenicity of the tumor and may induce a similar phenotype to that of POLE-mutated or MMR-deficient tumors, that may play a key role in endometrial carcinogenesis." (PMID 34257552, 2021). "In addition, POLE mutations accompanied by an ultra-tumor mutation burden present favorable clinical outcomes." (PMID 34439385, 2021). "Here, we sequenced normal tissue and tumor DNA from individuals with germline POLE/POLD1 mutations." (PMID 34594041, 2021). "In endometrial carcinoma, a syngeneic model found that the PoleP286R allele in the endometrium enhances anti-tumor immune response and tumor regression, suggesting that POLE-driven cancers may be more sensitive to ICB." (PMID 33918476, 2021). "To elucidate which genomic alterations best define pathogenic somatic POLE mutations (which we use in this context to mean very likely causal for tumour ultramutation), we used data from 530 ECs profiled by TCGA, including those reported in the 2013 publication." (PMID 31829442, 2020). "However, targeted panel sequencing did identify six cases of high tumor mutational burden for which subsequent POLE sequencing confirmed the presence of POLE mutation." (PMID 33256706, 2020). "Given the frequency of p.Pro286Arg and p.Val411Leu in our subset of cases with high tumor mutational burden and the association between these hotspot mutations and POLE ultra-mutated tumors, it is more likely that these tumors represent a POLE ultra-mutated subgroup." (PMID 33256706, 2020). "In addition to the age factor and the trend towards lower BMI, patients with POLE-mutated tumours are more often current or former smokers." (PMID 30917185, 2019). "Outcome in POLE-mutated tumours was excellent in cases with hotspot mutations." (PMID 30917185, 2019). "In summary, the POLE-mutated tumour cases had a better outcome compared to the rest of the cohort." (PMID 30917185, 2019).
tumor (continued). "The existence of a POLE mutation makes a tumour susceptible to acquiring additional mutations and may accelerate the transition from precancerous lesion to cancer." (PMID 30917185, 2019). "Several studies of EMCA cohorts have indicated that patients with POLE-mutated tumours are younger." (PMID 30917185, 2019). "Thirty-eight tumours had at least one hotspot POLE mutation." (PMID 30917185, 2019). "In addition, patients with tumor DNA repair deficiencies such as POLE and POLD mutations, are considered good candidates for checkpoint immunotherapy." (PMID 31658756, 2019). "In addition to the characteristic of a high mutation rate, the POLE-mutated tumours as classified by the TCGA have specific nucleotide missense mutations such as TCT→TAT and TCG→TTG mutations." (PMID 30917185, 2019). "This study of the molecular and genomic mutational basis of hypermutator tumours harbouring POLE mutations allowed us to describe mutation footprints that could be classified according to POLE-dependent/-independent and indefinite periods." (PMID 29880869, 2018). "Strikingly, in POLE‐mutant tumours, almost all known cancer driver genes showed evidence of the POLE consensus mutational signature, with the notable exception of POLE itself, consistent with the postulate that the POLE signature is a direct effect of the polymerase proofreading mutation." (PMID 29604063, 2018). "POLE-mutated samples were first extracted from more than 2,000 Japanese patients with cancer followed by confirmation of whether these tumours possessed characteristics similar to those reported in previous studies." (PMID 29880869, 2018). "Tumors harboring POLE mutations represent another phenotype with high tumor mutational burden that may predict response to PD-1 blockade." (PMID 29357948, 2018). "Defective DNA polymerase ε (POLE) proofreading leads to extensive somatic mutations that exhibit biased mutational properties; however, the characteristics of POLE-mutated tumours remain unclear." (PMID 29880869, 2018). "This correlation is consistent with the idea that the chance of any particular POLE mutant cell lineage developing into a tumor (and, thus, the chance of the POLE mutation being detected by sequencing of tumor samples) is proportional to the severity of the mutator phenotype." (PMID 29352080, 2018). "Thus, in addition to its clinical relevance, the demonstration that the POLE mutator phenotype operates from the first stages of tumour initiation would also reveal a novel pathway of sporadic tumourigenesis." (PMID 29604063, 2018). "Activation of HIF1A under hypoxia leads to a decrease of HR function; therefore, POLE-category tumours may compromise HIF1A activity via somatic mutations in itself and related genes to maintain the function of HR repair." (PMID 29880869, 2018). "If POLE mutations are late events, their consequences may be restricted to a subclone of tumour cells, the targeting of which may fail to meaningfully alter tumour behaviour." (PMID 29604063, 2018). "Furthermore, all of our results are based on the analysis of a single sample of each cancer, meaning that the effects of intratumour heterogeneity on the pattern of driver mutations and clonal neoantigens in POLE‐mutant tumours require further definition." (PMID 29604063, 2018). "Paired-tumor tissue was only available from the patient carrying the POLE p.Val474Ile variant." (PMID 28423643, 2017). "Basket trials stratifying patients according to tumor molecular alterations such as POLE mutations should be initiated to investigate whether these patients may also benefit from checkpoint inhibition." (PMID 28344870, 2017). "We also propose a mutator phenotype occurring specifically at 5mCs that results from POLE exonuclease domain mutation—a phenotype that we implicate in potentially driving tumour growth through the formation of specific mutation hotspots in key cancer-associated genes." (PMID 28531315, 2017).
tumor (continued). "Given the association between benefit from immune checkpoint inhibitors and tumor mutation burden, our study also suggests that the few patients with advanced or recurrent POLE proofreading-mutant cancers may be promising candidates for these agents." (PMID 27141333, 2016). "As many local EC recurrences are salvageable with therapy, we next examined whether cancer-specific survival (CSS) varied according to tumor POLE mutation." (PMID 25505230, 2015). "POLE defect induced mutations can also elicit an anti-tumor response, suggesting that POLE mutations may be another predictive marker for response to anti-PD-1 or anti-PD-L1 immunotherapy." (PMID 26517354, 2015). "The strong association of POLE mutations with high tumor grade caused us to hypothesize that their apparent prognostic effect would be most evident in this group, who are commonly considered for treatment intensification." (PMID 25505230, 2015). "Another point against a classical tumor suppressor model is the fact that only a minority of tumors with POLE or POLD1 EDMs show LOH or other inactivating mutations that could act as ‘second hits’." (PMID 24583393, 2014). "However, the p.Asn363Lys mutation reported on here clearly demonstrates that mutations in POLE can predispose carriers to a broad spectrum of tumours." (PMID 24788313, 2014). "Interestingly, a growing number of clinical cases have reported favorable outcomes from a subtype of supposedly non-responder microsatellite stable (MSS) CRC, characterized by DNA polymerase ε (POLE) proofreading domain mutations with high tumor mutational burden (TMB)." (PMID 40873566, 2025). "Furthermore, POLE/POLD1-mutated tumors show a high tumor mutational burden, and the identification of these genetic alterations could be used to select patients who are suitable for immunotherapy treatment." (PMID 39684352, 2024). "It has been proposed that differential expression levels of the WT and mutant POLE alleles in the course of cancer progression may allow transient stages of hypermutation that promote tumor growth together with a threshold limiting excessive mutation load to maintain fitness." (PMID 37891003, 2024). "However, the anti-tumor mechanism of POLE mutations remains largely elusive." (PMID 38238314, 2024). "Notably, in both tumours with POLE mutations, PTEN mutations were also present." (PMID 37175518, 2023). "However, an analysis of tumours from children with biallelic germline MMR deficiency demonstrated a subset of tumours with remarkably high mutation burdens (>250 mutations/Mb) that also had a somatic mutation in POLE or POLD1." (PMID 36010882, 2022). "POLE proofreading mutations might elicit an anti-tumor response." (PMID 36357827, 2022). "This approach will aim to direct those women who may not benefit from platinum to alternative regimens, for instance immune checkpoint inhibitors for POLE mutated or mismatch repair‐deficient tumours, and hormonal therapy or PI3K‐AKT‐mTOR inhibitors for nonspecific molecular profile (NSMP) cancers." (PMID 35429348, 2022). "To reveal the molecular mechanism underlying the role of POLE mutations in endometrial cancer, we selected four hotspot EDMs, including P286R, V411L, R375Q, and P452L, and assessed their pathogenicity based on the effects on catalytic activities of Polε and tumor cell behavior." (PMID 36313640, 2022). "Interestingly, the POLE hypermutation signature, albeit with a lower total mutation count and only one read supporting the p.A456P mutation, was also observed in the primary tumor of this patient (VAF 0.07)." (PMID 35982066, 2022). "Therefore, different POLE mutation sites can lead to different degrees of tumor mutation load." (PMID 35780178, 2022).
tumor (continued). "Recent evidence has clarified that several factors may determine a high-TMB in different neoplasms, including polymerase-epsilon (POLE) mutations, environment-based etiologies such as tobacco smoke, polycyclic aromatic hydrocarbons and UV exposure, or the presence of MSI." (PMID 34206554, 2021). "The proofreading potential of POLE is essential for ensuring replication fidelity, and its disruption by the pathogenic heterozygous mutations found in cancers leads to an ultra-hypermutated phenotype of tumours, with the highest burden of single-nucleotide variants among human cancers." (PMID 34034807, 2021). "Interestingly, these tumors are characterized as either microsatellite instable (MSI) or harboring POLE mutations; thus, co-occurrence could represent a “passenger phenomenon” in this specific tumor setting." (PMID 32242058, 2020). "In conclusion, we provide in silico support for the hypothesis that rare functionally-disruptive alterations in BLS genes may permit acquisition of high tumor mutation burdens, particularly in the context of mutation-prone genetic backgrounds such as POLE mutants." (PMID 31064401, 2019). "In order to increase the accuracy of the impact from POLE mutations and minimize the interference of hypermutated status on patient prognosis, we excluded hypermutated phenotypes (more than 500 mutations per sample) and found that the total tumor mutational burden decreased significantly." (PMID 31864301, 2019). "Importantly, the data thus far regarding POLE-mutant EC may be applicable to other tumor types harboring POLE mutations." (PMID 28344870, 2017). "Notably, this ultramutated tumor presented three other somatic missense variants in POLE located far away from the exonuclease domain (p.R1111Q, p.S681R and Y1889C) that could be promoting even a stronger effect." (PMID 28423643, 2017). "Interestingly, the POLE p.Asp301Asn and p.Ser459Phe mutations were found in the same tumor." (PMID 29072370, 2017). "With the recent advent of immunotherapy, microsatellite (MSI) status, tumor mutation burden (TMB), and POLE mutations, particularly those leading to high TMB, have gained importance in CRC." (PMID 40310397, 2025). "Research indicates that POLE and POLD1 mutations are linked to a higher TMB, which can potentially enhance the tumor’s visibility to the immune system, thereby improving the response to ICIs." (PMID 40575168, 2025). "Predictive biomarkers such as tumor mutational burden (TMB) and PD-L1 expression are crucial for optimizing patient selection, while hypermutated pMMR tumors with POLE mutations represent emerging therapeutic opportunities." (PMID 40700298, 2025). "Our in vitro experiments indicate that POLE suppression blocks tumor growth and cellular division in NCC_CDS1_X1_C1 and NCC_CDS2_C1 cells." (PMID 40760094, 2025). "The results also revealed that the TMB scores were higher in patients with POLE mutations than in WT patients, suggesting that POLE mutations may lead to the production of neoantigens, which can trigger an immune response and potentially enhance the immunogenicity of the tumor." (PMID 39931062, 2025). "Mechanistically, POLE loss increases DNA damage and induces p21-mediated cellular senescence to limit CIC::DUX4 tumor growth in vitro and tumor formation in vivo." (PMID 40760094, 2025). "Biomarker-driven Strategies:Identification of predictive molecular biomarkers for immunotherapy response in MSS CRC, including previously discussed tumor-infiltrating lymphocytes (TILs), POLE/POLD mutations, and tumor mutational burden (TMB)." (PMID 40308511, 2025).